EPO (erythropoietin)
Diseases named in the same sentence as EPO in open-access papers (continued):
Sharing a sentence is not in itself a finding about the gene and the disease.
carnitine deficiency (2 papers, 2020 to 2024). "In multiple regression analysis, the erythropoietin resistance index (p = 0.04, β = 0.293) was significantly correlated with carnitine deficiency." (PMID 32003308, 2020). "In this study, we found that carnitine deficiency was significantly correlated with the erythropoietin resistance index." (PMID 32003308, 2020). "In univariate analysis, the PD period (p = 0.03, β = 0.294) and erythropoietin resistance index (p < 0.01, β = 0.343) were significantly correlated with carnitine deficiency." (PMID 32003308, 2020). "Univariate and multivariate analyses showed that free carnitine level and the acyl carnitine/free carnitine ratio were significantly correlated with the erythropoietin resistance index in patients undergoing PD with carnitine deficiency." (PMID 32003308, 2020). "Multiple regression analysis showed that the erythropoietin resistance index was independently associated with carnitine deficiency (β = 0.283, p = 0.04)." (PMID 32003308, 2020). "Additionally, carnitine deficiency is significantly correlated with the erythropoietin resistance index." (PMID 32003308, 2020).
cholangiocarcinoma (2 papers, 2013 to 2023). A carcinoma that arises from the intrahepatic biliary tree (intrahepatic cholangiocarcinoma) or from the junction, or adjacent to the junction, of the right and left hepatic ducts (hilar cholangiocarcinoma). "RiskScore of cholangiocarcinoma patients with 10 genes calculated followed the formula: The RiskScore=0.429*VEGFC -0.434*NFKBIA-0.884*NLRX1+0.54*AKT1+0.629*CSRP1+0.406*EPO+0.833*IL31RA+1.023*LEP+0.341*MUC4+0.363*SEMA4B." (PMID 36817485, 2023). "Among all 10 prognostic specific immune-related genes, 4 genes (AKT1, EPO, MUC4, VEGFC) were considered as important predictors of relapse-free or overall survival and were implicated in immune microenvironment-related pathogenesis of cholangiocarcinoma." (PMID 36817485, 2023). "A progressive increase of EPO and EpoR mRNA can already be observed in cholangiocarcinoma." (PMID 36817485, 2023). "An analysis of the EPO/EpoR axis was also performed on human cholangiocarcinoma (CC) cell lines." (PMID 23052842, 2013).
choroidal neovascularization (2 papers, 2018 to 2021). An eye disorder described by the growth of new blood vessels that originate from the choroid through a break in the Bruch membrane into the sub–retinal pigment epithelium (sub-RPE) or subretinal space. "We plan to determine if EPO-R76E stimulated choroidal neovascularization (CNV) using the laser-induced CNV model." (PMID 34070383, 2021). "To test the role of EPO signaling, we used human EPOR knock-in mice with the mWtEPOR gene replaced by either the human EPOR gene (hWtEPOR) or a mutated human EPOR gene (hMtEPOR) in a laser-induced choroidal neovascularization (LCNV) model." (PMID 29391474, 2018). "We wished to investigate the role of EPO in choroidal neovascularization (CNV), a feature of neovascular AMD, and proposed the hypothesis that EPOR signaling affects choroidal macrophages causing them to facilitate the development of CNV through increased cytokine expression." (PMID 29391474, 2018).
chronic progressive multiple sclerosis (2 papers, 2008 to 2021). A form of multiple sclerosis characterized by a progressive deterioration in neurologic function which is in contrast to the more typical relapsing remitting form. "Similarly, an increase in cognitive performance upon EPO in patients with chronic progressive multiple sclerosis occurred independently of changes in hemoglobin levels, and persisted for months after termination of EPO treatment." (PMID 18782446, 2008).
collagen vascular disease (2 papers, 2008 to 2024). "Although data for the exact market share of biosimilars in the treatment of rheumatic diseases in Greece are not available, a previous study has estimated that, of all patients that receive therapy with erythropoietin (EPO), only 12% are treated with biosimilars." (PMID 39886285, 2024).
congenital anemia (2 papers, 2023 to 2024). Anemia, the cause of which is present at birth. "The newborns were distributed to different groups based on perinatal characteristics, such as sex, GA category, BW category, 1- and 5 min Apgar score categories, LDH within range, aPTT within range, PT within range, congenital anemia, and iron and EPO treatment." (PMID 38136044, 2023).
diabetic autonomic neuropathy (2 papers, 2019 to 2022). Autonomic neuropathy that is caused by diabetes mellitus. "Impaired O2 sensing in EPO production may be due to the following: diabetic autonomic neuropathy, reduced stabilization of HIF-1, the adverse effects of medications of RASi, and reactive oxidative stress (ROS) related EPO insufficiency." (PMID 35453626, 2022).
diabetic foot ulcer (2 papers, 2023 to 2025). "Currently, a Phase II clinical trial is ongoing, investigating the use of an erythropoietin/isosorbide dinitrate loaded cryogel scaffold for treating diabetic foot ulcers." (PMID 37514023, 2023).
edema (2 papers, 2012 to 2016). An abnormal accumulation of fluid beneath the skin, or in one or more cavities of the body. "The experimental results showed that the water content in the cerebral hemisphere of the rats in the EPO treatment group at each time point was markedly reduced (P<0.01) compared to the control group, suggesting that EPO decreased traumatic brain edema." (PMID 23226759, 2012). "Oedema was found in the adrenal medulla of all the animals, including those treated with EPO." (PMID 27504455, 2016). "In addition, this study also demonstrated that EPO has the potential to reduce the water content of brain tissue, indicating that EPO reduces traumatic brain edema." (PMID 23226759, 2012).
endometrial cancer (2 papers, 2016 to 2024). Primary or metastatic malignant neoplasm involving the endometrium (mucous membrane that lines the endometrial cavity). "The progression and enhanced aggressiveness of endometrial cancer may be facilitated by hypoxia-inducible autocrine erythropoietin signaling." (PMID 38337488, 2024). "In endometrial carcinomas, elevated erythropoietin expression might be a stand-alone predictive or prognostic feature." (PMID 38337488, 2024). "CD4, EPO, SOS1 and IFNA1 are related to several cellular mechanisms such as hematopoietic cell lineage determination, gonadotropin-releasing hormone (GnRH) signaling, cytokine-cytokine receptor interactions and endometrial cancer." (PMID 27832168, 2016).
erectile dysfunction (2 papers, 2022 to 2025). Persistent or recurrent inability to achieve or to maintain an erection during sexual activity. "CKD disrupts the endocrine function of the kidneys, resulting in disorders of glucose and lipid metabolism and erectile dysfunction in men, and the impaired synthesis of erythropoietin (EPO) and activated vitamin D leads to the development of renal anemia and renal bone disease." (PMID 40636262, 2025). "On a bilateral cavernous nerve injury rat model, the present stem cell‐EPO‐hydrogel implanted strategy could significantly alleviate erectile dysfunction." (PMID 36176612, 2022).
Erythema (2 papers, 2011 to 2022). Redness of the skin, caused by hyperemia of the capillaries in the lower layers of the skin. "Splenomegaly and erythema are recognized signs of activation of the oxygen-VHL/HIF/EPO pathway, and they have been reported previously in transgenic mice overexpressing EPO." (PMID 21811636, 2011).
erythroblastopenia (2 papers, 2014 to 2024). "Erythroid hypoplasia (EH) is a rare complication associated with recombinant human erythropoietin (rHuEPO) therapies, due to development of anti-rHuEPO antibodies; however, the underlying mechanisms remain poorly clarified." (PMID 25580431, 2014). "The production of anti-EPO antibodies and the inhibition of EPO-dependent erythroid cells are important mechanisms that might lead to erythroid hypoplasia (EH)/PRCA." (PMID 25580431, 2014).
falciparum malaria (2 papers, 2009 to 2023). "The prevalence of anti-EPO antibodies among pregnant women with Plasmodium falciparum malaria was high." (PMID 36989322, 2023).
folate deficiency anemia (2 papers, 2022). "Additionally, HbA1c levels strongly depend on the turnover of red blood cells: slow turnover (e.g., in iron, vitamin B12, or folate deficiency anemias) often results in higher, whereas fast turnover (e.g., hemolytic anemia and erythropoietin therapy) leading to lower HbA1c levels." (PMID 35340545, 2022).
gastric adenocarcinoma (2 papers, 2024 to 2025). "Our patient was a known CKD on erythropoietin 10,000 IU subcutaneously once a week for 3 months and had an active malignancy of stage IV gastric adenocarcinoma who developed a massive saddle PE." (PMID 41425520, 2025).
Gastrointestinal hemorrhage (2 papers, 2019 to 2025). Hemorrhage affecting the gastrointestinal tract. "Gastrointestinal hemorrhage is commonly seen in diseases of digestive organs, which potentially could stimulate erythropoietin (EPO) production and provoke anisocytosis." (PMID 31700048, 2019).
haemophilia (2 papers, 2019 to 2020). "Expression of recombinant factor IX (for hemophilia treatment) and human erythropoietin (EPO) has been reported." (PMID 31011551, 2019). "In 1986, Semenza started his postdoc training in medical genetics at Johns Hopkins School of Medicine, first working on haemophilia but later shifting his focus to erythropoietin (EPO) and developmental regulation of EPO expression, which was known to switch from foetal liver to adult kidney." (PMID 32579052, 2020).
hepatoblastoma (2 papers, 2014 to 2023). Hepatoblastoma (HB) is a malignant hepatic tumor and is the most common pediatric liver cancer. "Focus of EMH is frequently observed in hepatoblastomas and, similar to RCC, EPO has been previously detected in the tumor tissues of 11 out of 15 hepatoblastomas, i.e. tissues rich in EPO, as in hepatoblastoma." (PMID 24520308, 2014).
hereditary anemia (2 papers, 2019 to 2024). "Current treatments like erythropoietin (EPO) or glucocorticoids often fall short, especially for hereditary anemias such as Diamond-Blackfan anemia (DBA)." (PMID 39617757, 2024).
hyperhomocysteinemia (2 papers, 2021 to 2025). A serious metabolic condition caused by mutations in the MTHFR gene, medications, or nutritional deficiency. "This condition can result from multiple factors, including platelet abnormalities, endothelial factors, the use of erythropoietin, and hyperhomocysteinemia inflammation." (PMID 39958085, 2025).
hyperuricemia (2 papers, 2022 to 2024). An abnormally high level of uric acid. "While the hemolysis of mature erythrocytes, which lack nucleic acids, does not directly induce hyperuricemia, the erythropoietin response results in increased synthesis of precursors containing nucleic acids that break down during hemolysis, releasing uric acid and increasing uric acid levels." (PMID 38424614, 2024).
hypotension (2 papers, 2021 to 2023). "In a study of 42 haemodialysis patients, erythropoietin administration was not only associated with an elevation of haemoglobin but also with a rise in BP, while in patients with orthostatic hypotension, erythropoietin treatment elevated BP while standing." (PMID 38137695, 2023).
Impaired glucose tolerance (2 papers, 2014 to 2021). An abnormal resistance to glucose, i.e., a reduction in the ability to maintain glucose levels in the blood stream within normal limits following oral or intravenous administration of glucose. "The risk of NODAT development in patients receiving no or low-dose EPO with an HbA1c ≥ 5.2% was 6.34-fold higher than in patients with an HbA1c < 5.2%, which is higher than the reported odds ratio of impaired glucose tolerance based on a OGTT." (PMID 25386190, 2014).
infertile (2 papers, 2013 to 2024). "The available data indicate that NGF, EPO, and IGF-1 positively influence sperm motility, and lower levels of NGF or IGF-1 in seminal plasma are associated with infertility." (PMID 38792459, 2024). "They found that EPO protein was constitutively present in the seminal plasma of fertile and infertile males in a range from 1.5 mIU/mL to 45.0 mIU/mL, suggesting that it probably origins from the prostate and the seminal vesicle." (PMID 38792459, 2024). "The search was conducted using combinations of keywords related to “NGF”, “EPO”, “IGF-1”, “male reproductive system”, “sperm, “sperm motility”, “sperm vitality”, “infertility”, and “ART”." (PMID 38792459, 2024).
liver cirrhosis (2 papers, 2017 to 2024). "In individual samples, the mean expression level of EPO was 2.7-fold higher in liver cirrhosis samples compared to normal liver tissue." (PMID 28623280, 2017). "In order to test whether the splice variant hEPOΔ3 is also regulated under those pathological conditions, we established a realtime-PCR assay to quantify EPO and hEPOΔ3 transcript levels in human diseased (liver cirrhosis, ccRCC) and normal tissues." (PMID 28623280, 2017). "Thus, enhanced EPO and hEPOΔ3 expression in liver cirrhosis is likely explained by hypoxic mechanisms and the observed parallel enhancement in individual samples implies that EPO and hEPOΔ3 transcript expression are co-regulated in vivo." (PMID 28623280, 2017). "Within this panel, high EPO and hEPOΔ3 expression was found in one liver cirrhosis sample." (PMID 28623280, 2017).
metastatic disease (2 papers, 2015 to 2018). "PPGLs in these patients are often multiple or recurrent with elevated norepinephrine (NE), normetanephrine (NMN), DA, and erythropoietin (EPO) and once third of the patients present with metastatic disease." (PMID 30538672, 2018). "Main exclusion criteria are palliative surgery, metastatic disease, neoadjuvant chemoradiotherapy (5 × 5 Gy = no exclusion) and the use of Recombinant Human Erythropoietin within three months before inclusion or a blood transfusion within a month before inclusion." (PMID 26123286, 2015).
microangiopathic hemolytic anemia (2 papers, 2019 to 2022). "To date, the role of EPO in HUS, a systemic orphan disease with occurrence of microangiopathic hemolytic anemia and AKI, has not been systematically investigated." (PMID 36211426, 2022).
mineral bone disorder (2 papers, 2016 to 2024). "Treatment for ACKD usually involves several years of dialysis and targeted therapy for the side effects of CKD, such as phosphate binder therapy for mineral bone disorder and erythropoietin for renal anemia." (PMID 39469353, 2024).
Multiple Organ Failure (2 papers, 2021). A progressive condition usually characterized by combined failure of several organs such as the lungs, liver, kidney, along with some clotting mechanisms, usually postinjury or postoperative. "The administration of recombinant human erythropoietin has been proved to reduce acute lung injury and multiple organ failure/dysfunction in a rat model." (PMID 34436045, 2021). "The cause of death from multiple organ failure was significantly lower in the EPO group than the non-EPO group." (PMID 34831360, 2021).
Neurodevelopmental delay (2 papers, 2019 to 2021). "Both reported that erythropoietin decreased the risk of mortality and neurodevelopmental delay at 18 months." (PMID 34175900, 2021). "Whole body hypothermia (0.48; 0.33-0.71; 5 trials), selective head hypothermia (0.54; 0.32-0.89; 2 trials), and erythropoietin (0.36; 0.19-0.66; 2 trials) were more effective for reducing the risk of mortality and neurodevelopmental delay at 18 months (moderate to high certainty)." (PMID 31708771, 2019).
non-alcoholic fatty liver disease (2 papers, 2021 to 2025). "In a mouse model of non-alcoholic fatty liver disease, EPO administration in high-fat diet-induced obese mice reduced body weight, improved glucose tolerance and insulin sensitivity, and reduced lipid accumulation in liver and white adipose tissue (WAT)." (PMID 39996752, 2025). "In this regard, EPO stimulated lipid catabolism through the activation of JAK2/STAT5 signaling in peripheral adipose tissue and ameliorated non-alcoholic fatty liver disease via EPO/EPOR-induced STAT3 and STAT5 activation." (PMID 34281163, 2021).
oral mucositis (2 papers, 2023 to 2024). Inflammation of the mucous membranes of any of the structures in the mouth. "Allopurinol was potentially effective in the prevention of radiotherapy-induced oral mucositis; antimicrobial mouthwash and erythropoietin mouthwash were associated with a lower risk of development of severe oral mucositis induced by chemotherapy." (PMID 36661723, 2023). "Consistently, mucoadhesive gel based on trimethyl chitosan containing EPO expressed better healing and epithelization of chemotherapy-induced oral mucositis in rat models." (PMID 39294639, 2024).
ovarian tumor (2 papers, 2014 to 2017). "Sometimes thrombosis may be attributed to excessive production of erythropoietin by the kidney secondary to a pressure effect on the ureter by an ovarian tumor." (PMID 24963425, 2014).
parathyroid adenoma (2 papers, 2020 to 2021). "Erythropoietin could chronically stimulate the parathyroid glands and may result in the development of parathyroid adenoma or hyperplasia over time." (PMID 31979085, 2020).
peripheral nerve injury (2 papers, 2015 to 2022). Injury to a peripheral nerve. "The ~2-fold increase in MNCV of the EPO group compared to the saline or PLGA group and the improved SFI values demonstrated the recovery function of EPO in peripheral nerve injury." (PMID 25821803, 2015). "Such EPO-PLGA microspheres have great potential in clinical treatments of peripheral nerve injuries." (PMID 25821803, 2015). "Erythropoietin (EPO) has been demonstrated to exert neuroprotective effects on peripheral nerve injury recovery." (PMID 25821803, 2015). "Although the mechanism of EPO-mediated recovery is not fully understood, it has been demonstrated that the EPO receptor (EPOR) expressed by Schwann cells was the major target for EPO in peripheral nerve injury." (PMID 25821803, 2015). "The effects of a local thermoresponsive formulation of EPO on motor and sensory outcomes post-peripheral nerve injury were unknown." (PMID 36307805, 2022). "All these data together indicated strongly that the sustained EPO release achieved by the EPO-PLGA microspheres could prompt the recovery of peripheral nerve injury in rats." (PMID 25821803, 2015). "One recent study showed that EPO could promote the functional recovery and enhance nerve regeneration after peripheral nerve injury in rats." (PMID 25821803, 2015). "This might facilitate the study of the optimal dose and duration of EPO administration in the treatment of peripheral nerve injury." (PMID 25821803, 2015). "Albeit disappointing, the optimal dosage of EPO for the treatment of peripheral nerve injury is still unknown." (PMID 25821803, 2015).
periventricular leukomalacia (2 papers, 2013 to 2020). Periventricular leukomalacia (PVL) is a brain injury disorder characterized by the death of the white matter of the brain due to softening of the brain tissue. "When the patients were divided into two groups, as periventricular leukomalacia (PVL) and non-PVL group, the PVL group showed better outcomes in the pUCB group than in the EPO group on the GMPM, while the non-PVL group had better outcomes in the pUCB group on the BSID-II Mental scale." (PMID 23281216, 2013).
postpartum hemorrhage (2 papers, 2022 to 2025). Hemorrhage defined as a blood loss in excess of 500 mL after vaginal delivery or more than 1000 mL after a cesarean delivery. "Finally, Cluster 5 (purple) contained 26 terms primarily focused on maternal health conditions (e.g., nipple pain and postpartum hemorrhage) and their treatments and side effects (e.g., use of lanolin and erythropoietin)." (PMID 40129756, 2025).
pressure ulcer (2 papers, 2015 to 2024). "Indeed, in the very same experimental model, we have previously shown that treatment with recombining human erythropoietin (rhEPO) restored skin innervation density and C-fiber nociception and fully prevented pressure ulcer development in diabetic mice." (PMID 25888905, 2015).